ARID1A (AT-rich interaction domain 1A)
Diseases named in the same sentence as ARID1A in open-access papers (continued):
Sharing a sentence is not in itself a finding about the gene and the disease.
urothelial bladder cancer (7 papers, 2018 to 2025). "Among the identified subunits to date, the AT-rich interactive domain-containing protein 1A (ARID1A) is the most frequently mutated SWI/SNF component in urothelial bladder cancer." (PMID 33227989, 2020). "Recently, we revealed frequent genetic alterations of genes encoding for SWI/SNF subunits including ARID1A with a frequency of 26% in urothelial bladder cancer." (PMID 33227989, 2020). "In support of previously published data, showing that ARID1A truncating mutations result in ARID1A protein expression loss, we here provide further evidence for this assumption in urothelial bladder cancer." (PMID 30138427, 2018). "ARID1A truncating mutations were identified as the by far most common alterations of SWI/SNF complexes in urothelial bladder cancer." (PMID 30138427, 2018). "Subsequently, we applied the validated antibody to analyze a large cohort of urothelial bladder carcinomas (n = 362) and normal urothelial (NU) controls (n = 21) for ARID1A protein expression loss as a potential surrogate for ARID1A truncating mutations." (PMID 30138427, 2018). "Additionally, mutations in ARID1A were frequent in bladder urothelial carcinoma (BLCA), UCEC, LUAD, and lung squamous cell carcinoma (LUSC), while ARID5B mutations were prevalent in UCEC (10%)." (PMID 38920700, 2024). "Current ARID1A protein expression data in urothelial bladder cancer are contradictory, incomplete and conclusions drawn are limited due to small cohort sizes." (PMID 30138427, 2018). "We applied a validated ARID1A antibody conducting a comprehensive immunohistochemistry-based expression analysis in urothelial bladder cancer (n = 362) including carcinoma in situ (CIS) cases." (PMID 30138427, 2018). "We therefore aimed to perform a thorough, comprehensive IHC-based ARID1A protein expression analysis in a large cohort of urothelial bladder carcinomas including carcinoma in situ (CIS) cases." (PMID 30138427, 2018). "Current protein expression data for ARID1A in urothelial bladder cancer are inconsistent and incomplete." (PMID 30138427, 2018). "Here, we aimed to systematically dissect the frequency of genetic alterations in SWI/SNF subunit genes other than ARID1A that might contribute to inactivation of SWI/SNF complexes in urothelial bladder carcinomas." (PMID 30138427, 2018). "Moreover, direct evidence of ARID1A’s tumor suppressor capability in urothelial bladder cancer cells is scarce and we thus analyzed the effect of ARID1A protein loss on growth of urothelial cells as well as potential underlying mechanisms." (PMID 30138427, 2018). "For these reasons we started our analysis with a profound specificity validation of the ARID1A antibody applied and performed a thorough, comprehensive IHC-based ARID1A expression analysis in a large cohort of urothelial bladder carcinomas including carcinoma in situ (CIS) cases." (PMID 30138427, 2018). "Taken together, our preliminary in vitro data do neither support the concept of an anti-regulation between ARID1A and EZH2 in urothelial cells nor ARID1A-deficiency as a suitable predictive biomarker for EZH2-inhibitor treatment response in urothelial bladder cancer." (PMID 30138427, 2018). "Our comprehensive SWI/SNF subunit gene analysis revealed ARID1A truncating mutations, shown to be associated with reduction in ARID1A mRNA expression levels and ARID1A protein loss in previous studies, as the most common genetic alterations of SWI/SNF complexes in urothelial bladder cancer." (PMID 30138427, 2018). "CAF-derived miR-146a-5p can promote stemness and enhance chemoresistance in urothelial bladder cancer via regulating YY1/SVEP1 and ARID1A/PRKAA2 signal pathways." (PMID 38737906, 2024).
urothelial bladder cancer (continued). "In urothelial bladder cancer, the BAF complex-specific gene ARID1A has been identified as one of the top-altered genes with mutational frequencies ranging from 13 to 38% between studies." (PMID 30138427, 2018). "Taken together, we assume that ARID1A-deficiency (ARID1A truncating mutations and/or expression loss) is not a suitable predictive biomarker for EZH2 inhibitor treatment response in urothelial bladder cancer." (PMID 30138427, 2018). "ARID1A: No predictive biomarker for EZH2-inhibitor treatment response in urothelial bladder cancer?" (PMID 30138427, 2018). "Moreover, a synthetic lethality relationship between other SWI/SNF components including ARID1A and EZH2 has been revealed in several tumor entities but the potential of this concept for urothelial bladder cancer therapy is not known." (PMID 30138427, 2018).
adenomyosis (6 papers, 2019 to 2026). The growth of endometrial tissue inside the muscular wall of the uterine corpus. "ARID1A mutations, which are rarely observed in normal endometrium, were identified in 12% of adenomyosis in this study, as reported in another recent study." (PMID 40679511, 2025). "Based on these and our IHC results, we speculated the occurrence of PTEN loss in some uterine endometrial glands, with the clones being the source of adenomyosis and partial ARID1A loss causing gigantism." (PMID 41574315, 2026). "In adenomyosis, the most frequently mutated genes included KRAS (34.1%), PIK3CA (12.2%), ARID1A (12.1%), and FBXW7 (9.8%)." (PMID 40679511, 2025). "The mutation frequencies per subject, regardless of sampling depths, were as follows: in adenomyosis, KRAS: 33.3%, PIK3CA: 14.3%, and ARID1A: 14.3%, and in uterine endometrium, KRAS: 66.7%, PIK3CA: 57.1%, ARHGAP35: 52.4%, PPP2R1A: 33.3%, PIK3R1: 28.6%, and FGFR2: 19.0%." (PMID 40679511, 2025).
carcinoids (6 papers, 2017 to 2025). "In fact, although mutation rates of EIF1AX and ARID1A are in line with those of typical carcinoids, a higher prevalence of MEN1 mutations is observed in atypical carcinoids as compared with typical carcinoids, reaching 25%." (PMID 33641055, 2021). "This included HRAS (11p15) amplification on chromothriptic chromosome 11, KRAS (12q12) and ERBB3 (12q13) amplification on chromosome 12, as well as deletions of key carcinoid-associated tumor suppressor genes MEN1 (11q13) and ARID1A (1p36) on chromosomes 11 and 1, respectively." (PMID 39185963, 2025). "No EGFR or KRAS driver mutations were found in carcinoid histology, whereas an enrichment was found for driver mutations in ARID1A." (PMID 38798417, 2024).
head and neck cancer (6 papers, 2014 to 2023). A primary or metastatic malignant neoplasm affecting the head and neck. "Furthermore, we examined the correlation between ARID1A mutations and OS in individual cancer types in the Samstein cohort and found that ARID1A mutations were associated with a better OS in head and neck cancer (log-rank test, P = 0.01)." (PMID 31277418, 2019). "Co-occurrence of mutations of this gene and those of the PI3K pathway are reported to occur in endometrial and head and neck cancers, and ARID1A mutations may impact upon PI3K pathway activity." (PMID 25159823, 2014). "Given its immunomodulating effects and the increasingly important link between EGFR inhibitory therapies and tumor immune microenvironment, ARID1A changes may provide clues for optimizing immune checkpoint inhibitor therapy in head and neck cancers." (PMID 36362284, 2022).
mucinous carcinoma (6 papers, 2014 to 2023). "Concerning ARID1A expression, our results are in line with the TCGA dataset in which high ARID1A was reported in invasive and mucinous carcinomas, thereby suggesting its involvement in breast carcinogenesis." (PMID 33276477, 2020). "In TCGA dataset, elevated ARID1A gene expression was found in invasive carcinoma and mucinous carcinoma." (PMID 26904685, 2016). "In our study, among the 90 mucinous adenocarcinoma cases, the deletion ratios of SMARCA4, SMARCA2, and ARID1A subunits were 6.7%, 5.6%, and 4.5%, respectively." (PMID 35289322, 2022).
mucinous ovarian cancer (6 papers, 2018 to 2025). An invasive malignant neoplasm that arises from the ovary and is characterized by the presence of malignant epithelial cells that contain intracytoplasmic mucin and may resemble the epithelial cells of the endocervix or gastrointestinal tract. "We identified several genes known to be mutated in ovarian mucinous carcinomas, including ERBB2, ARID1A, and CREBBP." (PMID 40981433, 2025).
ovarian endometriosis (6 papers, 2020 to 2025). A non-neoplastic disorder characterized by the growth of endometrial tissue in the ovaries. "Combined with our previous study, which showed a frequency of 10% of ARID1A mutations in ovarian endometriosis, ARID1A mutations were also assumed to contribute to the progression of ectopic endometrium." (PMID 40679511, 2025). "All ARID1A mutations identified in ovarian endometriosis were heterozygous mutations, and ARID1A protein expression was retained in all ovarian endometriosis samples despite loss-of-function mutations." (PMID 33809880, 2021). "It is necessary to assess ARID1A protein expression in ovarian endometriosis samples with ARID1A mutations in independent data sets." (PMID 32868822, 2020). "In conclusion, we clarified that ARID1A protein expression was retained in ovarian endometriosis samples harboring ARID1A loss-of-function mutations." (PMID 32868822, 2020). "To clarify the significance of ARID1A inactivation in the development of EAOC, we investigated whether ARID1A is expressed in ovarian endometriosis with an ARID1A loss-of-function mutation." (PMID 33809880, 2021). "In this study, the sample size of ovarian endometriosis patients with ARID1A mutations was limited." (PMID 32868822, 2020). "Although our recent genomic study clarified that ARID1A loss-of-function mutations were detected in 13% of ovarian endometriosis, an association between the ARID1A mutation status and ARID1A protein expression in ovarian endometriosis remains unclear." (PMID 32868822, 2020). "The significance of ARID1A mutations in the malignant transformation of ovarian endometriosis remains unclear." (PMID 32868822, 2020). "Further driver events may be needed for the malignant transformation of ovarian endometriosis with ARID1A loss-of-function mutations." (PMID 32868822, 2020). "Another study revealed that somatic mutations specifically in cancer-associated genes were observed in 4% of ovarian endometriosis samples, including KRAS p.G12V and PPP2R1A p.S256F along with two ARID1A nonsense mutations, p.Q403 * and p.G1926 *." (PMID 40364006, 2025). "Our previous study clarified that PIK3CA, ARID1A, KRAS, FBWX7, and PPP2R1A are also frequently mutated in ovarian endometriosis." (PMID 38067342, 2023). "We assessed ARID1A immunoreactivity in 15 frozen section samples derived from six ovarian endometriosis patients." (PMID 32868822, 2020). "In ARID1A-deficient individuals, epithelial HDAC6 expression was profoundly upregulated in endometriotic lesions compared to control endometria (p = 0.031), particularly in ovarian endometriosis (p = 0.037)." (PMID 40364006, 2025). "Next, we assessed ARID1A protein expression in 63 FFPE samples derived from 41 ovarian endometriosis patients without ARID1A mutations." (PMID 32868822, 2020).
renal cell carcinoma (6 papers, 2013 to 2025). "For example, in renal cell carcinoma, ARID1A-deficient cells showed decreased apoptosis and increased TGF-β1 (Transforming Growth Factor beta 1) protein expression, which promoted metastasis and epithelial–mesenchymal transition." (PMID 40429787, 2025). "ARID1A acts as a tumor suppressor gene in renal cell carcinoma (RCC)." (PMID 36890819, 2023).
biliary tract cancer (5 papers, 2016 to 2023).
chordoma (5 papers, 2011 to 2025). Chordomas are rare malignant tumors arising from embryonic remnants of the notochord in axial skeleton. "Mutations in three other SWI/SNF members—PBRM1, SETD2, ARID1A—have been identified as potential drivers in chordomas; however, the relevance of these mutations to chordoma etiology remains to be elucidated." (PMID 32733369, 2020). "It appears that a subset (20.3%) of chordoma is enriched with at least one SWI/SNF complex mutation: PBRM1, ARID1A, or SETD2." (PMID 39941902, 2025). "Some chordomas also exhibit alterations in genes related to chromatin remodeling, such as ARID1A and PBRM1." (PMID 39941902, 2025). "PBRM1 mutations were present in 8.3% (n = 9/116) of chordoma NOS cases and 7.1% (n = 1/14) of conventional chordoma, while ARID1A mutations appeared in 6.4% (n = 7/116) of chordoma NOS cases and 14.3% (n = 2/14) of conventional chordoma." (PMID 39941902, 2025). "A number of other known cancer genes were affected by rearrangements across the samples described here, including ARID1A in PD3807a (chordoma)." (PMID 21215367, 2011). "These mutations affect various subunits of the SWI/SNF chromatin remodeling complex, with ARID1A being the most frequently mutated gene, followed by SMARCA4, ARID1B, ARID2, PBRM1, and SMARCB1, mutations we have found to be common in adult chordoma." (PMID 39941902, 2025). "Interestingly, chordoma mutations in the PBRM1, ARID1A, or SETD2 genes are frequently missense mutations." (PMID 39941902, 2025). "Mutations in PBRM1, ARID1A, and SETD2 appear to be enriched in chordoma." (PMID 39941902, 2025). "Our findings of enrichments in SWI/SNF complex mutations, such as PBRM1, ARID1A, SETD2, and SMARCA2, indicate that epigenetic therapies may be effective in some chordoma cases." (PMID 39941902, 2025). "We identified driver events in further cancer genes not previously implicated in chordoma including recurrent mutation of the SWI/SNF complex sub-unit gene ARID1A (4/104 cases)." (PMID 29026114, 2017). "Chordomas commonly activate pathways such as EGFR, PDGFβ, IGFR1, IGF1, mTOR, MET, and PI3K and involve chromatin remodeling genes such as ARID1A, PBRM1, and SETD2." (PMID 39193055, 2024). "In this cohort, composed of 116 patients with chordoma NOS, 14 with conventional chordoma, and 3 with dedifferentiated chordoma, mutations in SWI/SNF complex genes (PBRM1, ARID1A, SETD2) were not significantly enriched or depleted across subtypes (p > 0.05)." (PMID 39941902, 2025).
esophageal cancer (5 papers, 2015 to 2025). A primary or metastatic malignant neoplasm involving the esophagus.
invasive breast carcinoma (5 papers, 2013 to 2023). A carcinoma that infiltrates the breast parenchyma. "Evidence indicates that partial loss of ARID1A expression is significantly correlated with poor disease‐free survival in patients with invasive breast carcinoma." (PMID 29392887, 2018). "Current studies have found that low ARID1A expression is related to the poor prognosis of invasive breast cancer." (PMID 33592583, 2021). "Using TCGA database, we found that ARID1A down‐regulation refers to a poor RFS probability in unclassified breast invasive carcinoma (BRCA) patients." (PMID 29392887, 2018). "The influence of mutation and copy number variation on the expression were statistically insignificant at mRNA level, and were, therefore, not considered the main causes for ARID1A mRNA low expression in invasive breast cancer." (PMID 23349767, 2013). "From the results, we speculated that the loss of ARID1A was due to hypermethylation, which is in accordance with a previous study proposing that promoter hypermethylation of the ARID1A gene is responsible for the low ARID1A mRNA expression in invasive breast cancers." (PMID 32878261, 2020). "Specifically, ARID1A decrease alters the three-dimensional structure of the RAB11FIP1 promoter region thus increasing its expression and facilitating invasive breast cancer." (PMID 36890819, 2023).
prostate tumors (5 papers, 2022 to 2025). "Instead, NF-κB-induced PMN-MDSC chemotaxis was found to be the culprit causing the metastatic outgrowth of Arid1a-deficient prostate tumors." (PMID 36435834, 2022). "We firstly assessed whether Arid1a loss affects the remaining SWI/SNF complex in mouse prostate tumors." (PMID 36435834, 2022). "As ARID1A mutations are believed to result in reduced gene expression, we performed immunohistochemical staining with a specific antibody against ARID1A, which revealed complete loss of expression in all tumor cells, further confirming the loss-of-function mutation of ARID1A in this prostatic tumor." (PMID 35125107, 2022). "This complex context-dependent role of ARID1A motivated us to investigate Arid1a using a GEMM system, where simultaneous loss of Pten and Arid1a in vivo produced aggressive and locally invasive prostate tumours." (PMID 39885328, 2025). "ARID1A immunostaining intensity was negatively associated with the GS and PSA level in prostate tumors." (PMID 36435834, 2022). "Together, these results reinforce the link between MDSC-high prostate tumors and reduced ARID1A activity." (PMID 36435834, 2022). "However, we found that ARID1A loss did not reduce Cxcl9 and Cxcl10 expression in PCa cells treated with IFN-γ or TNF-α and mouse prostate tumors." (PMID 36435834, 2022).
undifferentiated carcinoma (5 papers, 2019 to 2025). A usually aggressive malignant epithelial neoplasm composed of atypical cells which do not display evidence of glandular, squamous, or transitional cell differentiation. "ARID1A-deficient undifferentiated carcinoma exhibited cellular discohesion and rhabdoid morphology." (PMID 38378604, 2024). "In an animal model, 59% of mice with ARID1A and PTEN double knockout of mouse ovarian surface epithelium developed ovarian endometrioid or undifferentiated carcinomas, whereas mice with ARID1A knockout alone did not." (PMID 38275587, 2023).